CD44 (CD44 molecule (IN blood group))
Diseases named in the same sentence as CD44 in open-access papers (continued):
Sharing a sentence is not in itself a finding about the gene and the disease.
glioma (continued). "The ability of CAR to interfere with Nanog, Oct4, SOX2, CD44 and BMI1 expression is consistent with the effects of other natural compounds (e.g., adriamycin and diflourinated curcumin) to control the cancer stem cell bulk and the aggressiveness of glioma and pancreatic adenocarcinoma." (PMID 29123181, 2017). "The results that cleavage of cytomembrane CD44 was not coordinately increased along with MMP14 indicated that MMP14 might enhance glioma migration and invasion not through cleavage of CD44 but rather through activation of MMP family members." (PMID 27613828, 2016). "Since it has been shown that increased SP in gliomas correlates with unregulated CD44 expression and radiation resistance in the same murine GBM model, we examined whether CD44 expression is increased in PVA area when tumors from Cx3cr1GFP/GFP mice are compared to Cx3cr1GFP/+ and B6." (PMID 25987130, 2015). "As most of the putative glioma CSC associated markers (e.g. CD133, CD15, A2B5 and CD44) are not unique to tumour cells but are also expressed by stromal cells, we used spheroid-based xenografts in eGFP+ NOD/Scid mice for a distinct analysis of pure tumour cell populations." (PMID 24154962, 2014). "As CD44 is a receptor for hyaluronan (HA), and was identified and verified as overexpressed in GBM tissues, we explored the effects of HA-treatment on cell migration, proliferation, and cell cycle in glioma cells (U87 / U373) as well as normal human astrocytes (NHA)." (PMID 23855374, 2013). "However, the expression of CD44, a marker of glial progenitor cells widely expressed on the surface of glioma cells, was not detectably affected." (PMID 23630597, 2013). "However, it cannot be excluded that A2B5+CD44+GFAP+ glioma cells without detectable PDGFRα and O4 expression (e.g.: case #9) actually represent the expansion of ARP-like cells." (PMID 18398462, 2008). "However, further analysis found that NCR3LG1 shows negative relationship with CD44 in glioma, which may be partially explained by the low expression in malignant glioma and positive glioma survival biomarker of NCR3LG1." (PMID 35187044, 2021). "Versican has been found to be co-localised with hyaluronan, CD44 and tenascin in the pericellular matrix in tumours, and because of its ability to interact these modulators of invasion and EGFR, versican may contribute to the malignant properties of glioma cells." (PMID 17453002, 2007). "The expression levels of CD44 were higher in unmethylated glioma with IDH wildtype and glioma with 1p/19q non-codeletion." (PMID 36776876, 2023). "While no clinical trials have been performed on glioma patients, the CD44 inhibitor RG7356 induced modest clinical benefits in a trial of 65 patients with advanced CD44-expressing solid tumors." (PMID 36276147, 2022). "An increased invasion capability, associated with a reduced VEGF/VEGFR2 expression and increased vimentin and CD44 epithelial-mesenchymal transition markers in siTRPML2, but not in enforced-TRPML2 or ML2-SA1-stimulated glioma cells, was demonstrated." (PMID 35054871, 2022). "In contrast to glioma stem cells, U87 cells showed no overexpression of stem cell markers, such as SOX2, ZEB1, ATXN1, ALCAM, CD9, ITGA7, CD44 and CHI3L1." (PMID 34680293, 2021). "Hyaluronic acid/hyaluronan (HA), the main ECM component of the healthy brain, as well as their main receptors CD44 and RHAMM (receptor of hyaluronan-mediated motility) are also upregulated in glioma, but their exact role is not yet determined." (PMID 31003495, 2019).
glioma (continued). "Notably, confocal laser scan microscopy revealed increase in membranous co-localization of both moesin and CD44 in HA-treated glioma cells in comparison to no treatment controls, suggesting HA-induced moesin-CD44 interaction in glioma cells may be responsible for increase in migratory cells." (PMID 23855374, 2013). "In order to further investigate the possibility of synergistic or co-operative role between CD44 and CD155 in glioma invasion (not evidenced in this study) we plan to carry out additional, in-depth studies of signal transduction pathways." (PMID 22363471, 2012). "For example, in 2001, it was demonstrated that high-grade gliomas expressed higher levels of RHAMM and CD44 than low-grade lesions and that RHAMM inhibition hindered proliferation and migration of glioma cells, both in the presence and in the absence of HA-based ECM." (PMID 33744285, 2021). "One meta-analysis claims higher expression of CD44 that predicts poor survival in glioma particularly in those with WHO grades II and III glioma, and another clinical research discovers that higher tumor expression of CD44 acts as a negative prognosis indicator in patients with GBM." (PMID 35187044, 2021). "CD44 signaling enhances CSC-like phenotypes in glioma, however, in our experiments, this pathway does not mediate OPN-HIF-1α-driven self-renewal of HCC cells and further research of the role of CD44 signaling in self-renewal of OPN is warranted." (PMID 25749383, 2015). "Thus, they isolated glioma stem lines growing as floating neurosphere-like aggregates (positive for SOX2 and differentiating to GFAP-positive cells) and other ones growing as irregularly-shaped floating aggregates, with some adherent cells (positive for CD44 and negative for SOX2)." (PMID 30279357, 2018).
gastric cancer (371 papers, 2002 to 2026). A primary or metastatic malignant neoplasm involving the stomach. "The experimental results suggest that lncRNA CCAT2 upregulates the expression of CD44v6 by binding to ESRP1, thereby mediating the selective splicing of CD44 and promoting the development of gastric cancer, which is associated with shorter patient survival." (PMID 40046628, 2025). "CD44 variant isoforms reportedly bind to xCT on the cellular membrane and stabilize xCT expression in mouse gastric cancer stem cells, increasing the uptake of cystine as an essential substrate for glutathione synthesis, preventing toxicity by ROS." (PMID 40002787, 2025). "In cancer, CD44 is highly expressed in gastric cancer and is associated with gastric immune invasion.CD44 can be used as a prognostic biomarker in gastric cancer." (PMID 40642092, 2025). "Specifically, we evaluated the potential regulatory influence of JMJD3 on the expression of key stemness markers, including OCT4, LIN28, SOX2, CD133, and CD44, which are associated with gastric cancer." (PMID 41184226, 2025). "In gastric cancer, polystyrene exposure associated with higher CD44 and ASGR2, aligning with stemness/adhesion and glycoprotein handling." (PMID 41378310, 2025). "The present study evaluated the levels of proteins associated with stemness after LA treatment of gastric cancer cells and revealed that LA suppresses cancer stemness through the Akt/Nrf2/CD44/SOX2 signaling axis." (PMID 40864800, 2025). "CD44-positive gastric cancer stem cells (CSCs) are less susceptible to ferroptosis, contributing to their survival and resistance to treatment." (PMID 40843357, 2025). "Elevated CD44 expression is also linked to immunosuppression in gastric cancer, potentially through recruitment of Tregs and M2-like macrophages and upregulation of immune checkpoints." (PMID 41031085, 2025). "It was concluded that combined, CD44 and Shh signalling pathways are critical indicators of tumour severity, patient survival, and the risk of recurrence in gastric cancer." (PMID 38920995, 2024). "CD44 expression rate was found to be as high as 80% in primary gastric cancer resection specimens, and gastric cancer with high CD44 expression was associated with higher level of clinicopathological features and worse prognosis." (PMID 36918410, 2023). "CD44 is highly expressed in gastric cancer and is an independent prognostic factor associated with immune invasion, which can be used as a candidate prognostic biomarker to determine the prognosis associated with gastric immune invasion." (PMID 36316684, 2022). "For example, ASPN was reported to enhance tumor invasion and cancer-associated fibroblasts via activation of the CD44-Rac1 pathway in gastric cancer." (PMID 36386304, 2022). "CAPZA1 promoted the expression of CD44 and epithelial splicing regulatory protein 1 (ESRP1), the latter which spliced CD44 into CD44 variant 9 (CD44v9), a marker of gastric cancer stem-like cells." (PMID 36526626, 2022). "Among a variety of tumour stem cell markers, CD44 is widely involved in immune invasion and is associated with the prognosis of various tumours, including gastric cancer." (PMID 36316684, 2022). "An example can be found in the generation of a phage display library that was screened against recombinant HEK-293 cells with the variant CD44 biomarker for gastric cancer cells." (PMID 35454775, 2022). "CD44 is often upregulated in gastric cancer and associated with increased metastatic potential and poor survival." (PMID 35864961, 2022). "Several studies focused on the CD44 variant 9 in the gastric cancer and variant 6 in the colon cancer." (PMID 34168979, 2021). "Elevated expression of CD44 protein is also linked to poor prognosis and distant metastasis in human gastric cancer, indicating the essential roles of TICs in gastric cancer progression." (PMID 34758833, 2021).
gastric cancer (continued). "CD44 variant 8-10 (CD44v8-10) has been identified as being predominantly expressed in gastric cancer cells and less in normal tissues." (PMID 33810350, 2021). "CD44 and its selected variants were further reported as markers of poor prognosis in gastric cancer patients." (PMID 34257584, 2021). "PLAP-1 is expressed in cancer-associated fibroblasts of scirrhous gastric cancer and promotes invasion through activation of the CD44-Rac1 pathway." (PMID 33654143, 2021). "Higher expression of CD44 variant 6 has been reported in gastric tumor with lymph node metastasis, suggesting that CD44 variant 6 plays a role in the metastasis of gastric cancer." (PMID 33563334, 2021). "Histopathological studies of human gastric carcinoma have associated high CD44 expression with tumor invasion, lymph node metastasis and patient survival, although the expression of CD44 in CGC has so far not been investigated." (PMID 34069167, 2021). "An SNP located within 3 ́UTR of CD44, rs8193,statistically associate with the risk of lymph node spreadand stage of gastric cancer in Iranian population." (PMID 31376327, 2020). "CD44 expression has been associated with gastric cancer disease progression and aggressiveness, revealing its importance in these types of malignancies." (PMID 31973075, 2020). "In gastric cancers, the knock-down of CD44 reduced sphere formation and caused decreased tumor growth in severe combined immunodeficiency mice." (PMID 32849491, 2020). "Several studies have reported that CD44-positivity is significantly associated with poor survival in gastric cancer patients, and presence of CD44-positive cancer stem-like cells especially at the invasive tumor front act as an indicator of poor prognosis." (PMID 30909497, 2019). "We established gastric cancer patient-derived cells (PDCs) to examine the contribution of CD44 splicing variant 9 (CD44v9)-positive cells in gastric cancer drug tolerance." (PMID 31607750, 2019). "We also analyzed the expression of the stem cell marker CD44, which has been associated with initiation and progression of gastric cancer and previous studies have shown that CD44+ cells are targeted during H. pylori infection." (PMID 30884828, 2019). "In gastric cancer high level miR-106b, miR-93, and miR-25 expression is associated with CD44 expression." (PMID 30211160, 2018). "The absolute quantification of four types of CD44 expression variants revealed that CD44v8-10 was the major isoform in gastric cancer cell lines except for MKN-28." (PMID 28694503, 2017). "Several studies have suggested the potential importance of CD44 polymorphisms as a risk factor and poor prognostic marker in various cancers, including gastric cancer." (PMID 29445738, 2017). "They demonstrated that ablation of CD44 induced loss of xCT from the cell surface and suppressed tumor growth in gastric cancer." (PMID 28253902, 2017). "Although CD44 polymorphism is very important for cancers, few reports showed the roles of CD44 polymorphism in colon and gastric cancer." (PMID 27323782, 2016). "To assess the aggressiveness of CD44, Shh, and Gli1 for gastric cancer, we established biomarker risk score system to evaluate the prognostic importance." (PMID 26839535, 2016). "In accordance with these results, univariate Cox regression analysis also revealed that CD44, Shh, and Gli1 status were associated with the prognosis of gastric cancer in our study." (PMID 26839535, 2016). "Most studies confirm that high CD44, Shh, and Gli1 expression is significantly associated with poorer clinicopathological parameters and worse overall survival in gastric cancer." (PMID 26839535, 2016). "Colon cancer has 36.36% C > T and 36.36% G > A mutation in CD44 coding strand, and 23.08% C > T and 23.08% T > C mutation in gastric cancer." (PMID 27323782, 2016). "LncRNA-uc002kmd.1, also named GAPLINC, was reported to be associated with CD44-dependent cell invasiveness and poor prognosis of gastric cancer." (PMID 27259250, 2016).
gastric cancer (continued). "Subsequently, several tumors, including colon cancer, Hodgkins lymphoma, gastric cancer, and melanoma, have been screened for CD44 isoforms, indicating that certain CD44 variants have crucial roles for tumor progression." (PMID 25999946, 2015). "Loss of E-cadherin expression and aberrant expression of vimentin and the known gastric cancer stem cell maker CD44 were significantly associated with aggressive clinicopathologic features." (PMID 25441488, 2014). "CD44 is positively and significantly associated with tumor metastasis, recurrence, and mortality in gastric cancer." (PMID 25441488, 2014). "After adjusting for sex, age, TNM stage, and lymphovascular invasion, CD44(+) patients had a significantly higher risk of gastric cancer-related death compared with CD44(−) patients (odds ratio (OR) = 1.57; 95% CI: 1.05–2.36; P = 0.029)." (PMID 25212506, 2014). "In conclusion, expression of CD44 was associated with poor survival in patients with gastric carcinoma." (PMID 25212506, 2014). "Numerous studies have focused on the diagnostic and prognostic significance of CD44 expression in human tumors, especially gastric cancer." (PMID 22839505, 2012). "Expression of CD44 variants in gastric cancer patients such as CD44v6 and CD44v9 are associated with progression of gastric cancer." (PMID 23217022, 2012). "Because highly frequent amplification of ERBB4, C-MET and CD44 was demonstrated in gastric cancer, their association with clinicopathological characteristics was analyzed in a cohort of clinically well-characterized gastric cancers." (PMID 22606006, 2012). "CD44 expression is linked to poorer clinical outcomes in patients with gastric cancer." (PMID 40864800, 2025). "CD44 expression in gastric cancer cells is associated with chemoresistance." (PMID 40518514, 2025). "CD44v8-10, a variant of CD44, plays an important role in gastric cancer, and its mechanism of action may be through the enhancement of antioxidant capacity." (PMID 40110193, 2025). "Furthermore, expression of CD44 is associated with self-renewal and generation of differentiated progeny in gastric cancer cells." (PMID 36846589, 2023). "In addition, SALL4 bound to the CD44 promoter region and activated its transcription, and CD44 overexpression reversed the inhibition of gastric cancer cell proliferation, migration, and invasion caused by SALL4 knockdown." (PMID 37525212, 2023). "In gastric cancer, ablation of a CD44 variant (CD44v) diminishes membrane xCT and suppresses tumor growth accompanied by a greater expression of phospho-p38 MAPK and upregulation of p21 in the cancer cells that adopt a more differentiated and less proliferative state." (PMID 36457557, 2022). "In addition, CD44, Wnt2, Bmi1, Notch1, Oct4, Sox2, Nanog, C-mys, ABCG2, CXCR4 and other “stemness associated genes” are highly expressed in the CD44+ gastric cancer cell population." (PMID 36316684, 2022). "It has been reported that the expression of CD44 variant 9 could be utilized as a predictive marker for the recurrence in early gastric cancer (EGC) after endoscopic submucosal dissection (ESD)." (PMID 35418175, 2022). "A higher expression of CD-44 is found in many cancer types and the elevated level of CD-44 in serum is used as a diagnostic marker for estimation of the tumor burden in colon and gastric cancers." (PMID 33530291, 2021). "Detection of splice variants of CD44 in body fluids is already happening in several cancers and diseases like bladder cancer, endometriosis, gastric cancer and colon cancer on the other hand detection of CD44 levels in healthy and oral SCC patients saliva and serum was found inconclusive." (PMID 34257584, 2021). "In vitro assay illustrated that E2F1 could regulate the expression of stemness-associated genes, such as BMI1, OCT4, Nanog, and CD44, and maintain the tumor spheroid formation ability of gastric cancer cells." (PMID 33986804, 2021).